IL6 (interleukin 6)
Diseases named in the same sentence as IL6 in open-access papers (continued):
Sharing a sentence is not in itself a finding about the gene and the disease.
thrombosis (continued). "In both human and animal studies, an association between the occurrence of deep vein thrombosis (DVT) and increased expression of IL-6 has been demonstrated." (PMID 34069173, 2021). "The magnitude of hs-CRP and IL-6 reduction found in the current study is similar to the effect of canakinumab used in the Canakinumab Antiinflammatory Thrombosis Outcome Study (CANTOS)." (PMID 32866166, 2020). "Its role in the vasculature is not well understood, but it has recently been shown to play a proinflammatory role in human venous thrombosis via its binding to galectin 3, enhancing leukocyte adhesion to the vessel wall and increasing IL-6 expression." (PMID 28319050, 2017). "CC genotype showed the increased levels of both hs-CRP and IL-6 in thrombosis patients with positive history of infection." (PMID 24363620, 2013). "The thrombosis cohort exhibited significantly higher values of pro-inflammatory markers IL-6 [55 pg./mL vs. 38 pg./mL, p < 0.02] and TNF-α [159 pg./mL vs. 110 pg./mL, p < 0.02] compared to the non-event cohort, suggesting an increased risk of developing a thrombus in the former." (PMID 40776916, 2025). "Importantly, IL-6 and procalcitonin, markers of a severe infection in progress, and D-dimers, markers of deep vein thrombosis, pulmonary embolism, as well as inflammation and infection, were higher in non-survivors compared to survivors." (PMID 40149514, 2025). "We hypothesized that patients with VTE and active cancer would show the highest values of both EV-TF and IL-6 because of the concurrent presence of these two potential procoagulant and proinflammatory conditions, such as active cancer and acute thrombosis." (PMID 39858477, 2025). "Higher plasma concentrations of IL-6 in patients with deep vein thrombosis." (PMID 40299499, 2025). "It has been shown that inflammatory factors such as IL-6 are highly correlated with thrombosis, and therefore, anti-inflammatory activity in the vascular system may be another strategy to prevent or control thrombosis." (PMID 37140597, 2023). "However, the relationships between thrombosis and IL6 and CRP, which were included in the score, have been previously explored." (PMID 36835788, 2023). "Similarly, in patients with deep vein thrombosis, the treatment with dabigatran or edoxaban resulted in a 2.8 times reduction of the IL-6 expression levels in the peripheral lymphocytes." (PMID 36675819, 2023). "Our laboratory, and others, has also shown that IL-6 might play an active role in venous thrombosis (VT) resolution, partly mediated by matrix metalloproteinase activity." (PMID 35647566, 2022). "Furthermore, both IL-6 and IL-1β have been reported to be involved in thrombosis in SARS-CoV-2 infection." (PMID 36035409, 2022). "In such a situation, a large amount of cytokines and chemokines are secreted, for example TNF-α, IL-1, IL-6, IL-8, which stimulate other cells of the immune system and the formation of a large inflammation focus, and, as a result, micro- and macro-vascular thrombosis leading to organ failure." (PMID 35328208, 2022). "•Key Findings: In a stasis model of deep vein thrombosis, although global deletion was associated with decreased vein wall fibrosis, anti–IL-6 agents did not affect vein wall fibrosis." (PMID 35647566, 2022). "Thrombosis induces the release of cytokines including IL-6, tissue factor, and TNF-α by activating endothelial cells, and inflammation accelerates hypercoagulability state and leads to endothelial damage and platelet aggregation, thus further aggravating the development of DVT." (PMID 32441737, 2020). "Similarly, in vivo, the plasma IL-17B, IL-6, and TNF-α were significantly increased after thrombosis in WT mice, and the plasma IL-6 and TNF-α was increased more significantly after the intervention of IL-17B protein on the basis of ligation of IVC (all P < 0.05)." (PMID 36046722, 2022).
thrombosis (continued). "Interleukin-6 concentration is not evaluated in daily clinical practice, whereas D-dimer might be either associated with the occurrence of thrombosis or with infection." (PMID 33272355, 2020). "Trans-endothelial migration of MNC was enhanced in HL, FL and DLBCL with thrombosis and reduced by inflammatory cytokine tumor necrosis factor alpha (TNF-α) that promoted platelet aggregation like interleukin-6 (IL-6) in HL and FL." (PMID 42041535, 2026). "Levels of circulating IL-6 and TNF- α were significantly higher in the thrombosis cohort compared to the non-thrombosis cohort (55 vs. 38, p < 0.02) and (159 vs. 110, p < 0.02) respectively." (PMID 40776916, 2025). "Recent research has shown that C29 markedly decreases the expression of inflammatory markers, including IL-6 and TNF-α, through the inhibition of the TLR2/NF-κB/COX-2 signaling pathway, which helps relieve traumatic deep vein thrombosis." (PMID 40510367, 2025). "Three patients with venous thrombosis were treated with glucocorticoid pulses combined with TNF-α inhibitors, and one patient was treated with IL-6 inhibitors." (PMID 38243321, 2024). "Inflammatory mediators, such as CRP, interleukins (IL-6 and IL-8), and tumor necrosis factor-alpha (TNF-α), play significant roles in both arterial and venous thrombosis." (PMID 39742171, 2024). "The levels of CRP, IL-6, and integrins β1, β2, and β3 in patients with acute arteriovenous thrombosis were higher than those in the control group, suggesting that inflammation is involved in acute arteriovenous thrombosis and may represent a shared pathway between arterial and venous thrombosis." (PMID 37998519, 2023). "Further, in univariate logistic regression analysis, admission to ICU and use of anti-IL6/anti-IL6R and corticosteroids were predictive of thrombosis occurrence." (PMID 36028857, 2022). "In particular, IL-6 seems to play a critical role in inflammation-related thrombosis, together with tumor necrosis factor-alpha (TNFα), interleukin 8 (IL-8), and C-reactive protein (CRP), representing powerful risk predictors for DVT." (PMID 35625609, 2022). "In the last decades, the relationship between deep vein thrombosis (DVT) and inflammation has been widely investigated, focusing on the role of IL-6." (PMID 35625609, 2022). "Combined treatment of miR-136-5p agomir and oe-IL-6 or combined treatment of miR-136-5p agomir and oe-CRP led to complete venous thrombosis versus the combined treatment of miR-136-5p agomir and oe-NC." (PMID 33188660, 2020). "In venous thrombosis, galectin-3 BP and galectin-3 play critical roles, possibly through IL-6 and PMN-mediated thrombotic mechanisms, and are potential biomarkers in human venous thrombosis." (PMID 31080833, 2019). "DIC is an illness caused by an uncontrollable systemic activation of the clotting cascade due to pro-inflammatory cytokines, such as IL-1β, IL-6, and TNF-α, followed by excessive consumption of clotting factors, microvascular thrombosis, and finally, thrombotic or hemorrhagic episodes." (PMID 38254870, 2024). "Initially, it was believed that IL6 did not play a role in venous thrombosis; however, as more research was conducted on its function, this statement was discarded." (PMID 37391801, 2023). "The baseline levels of IL-6, IL-10, VCAM-1, CCL19, BCA-1, IL-4, E-selectin, fractalkine, CXCL12, and GCP2 were found to differ statistically among the control, arterial thrombosis, AF-related venous thrombosis, and major bleeding groups (p < 0.05)." (PMID 36211709, 2022). "Furthermore, procyanidin-rich fractions have been found to downregulate the release of pro-inflammatory cytokines, including IL-8, IL-6, and TNF-α, in a rat model of deep vein thrombosis." (PMID 35630834, 2022). "Although IL-6 increase has been documented in venous thromboembolic diseases, the exact involvement of IL-6 signaling in deep vein thrombosis (DVT) has not been fully understood." (PMID 35625609, 2022).
thrombosis (continued). "Plasma levels of inflammation, angiogenic, and coagulation markers, including TF and IL6, in cancer with deep vein thrombosis (DVT) were higher than those in cancer without DVT." (PMID 35565252, 2022). "Our study revealed that several indicators were related to the severity of the disease, including platelet associated parameters (PLT, PCT, PDW, MPV, P-LCR), cytokine (IL-6), coagulopathy parameters (PT, PTA, INR, d-dimer, FDP), and thrombosis-related indicators (IP-10, MCP-1)." (PMID 33121429, 2020). "Plasma protein C, white blood cell counts, total cholesterol, fibrinogen, serum amyloid A, and IL-6 were not different amongst siProc treated mice with or without thrombosis." (PMID 30305662, 2018). "The model showed, with an SE of 83% and an SP of 62%, that age; sex; levels of D-dimer, leucocytes, and IL6 collected at admission; and levels of CRP collected during the first 24 h of hospitalization could predict thrombosis with an accuracy of 77% (95% CI 69.9–84.0%)." (PMID 36835788, 2023). "LP-HFY05 and dipyridamole could down-regulate NF-κB p65, IL-6, TNF-α, and IFN-γ expression in renal tissues of mice with thrombosis, and the effects of LP-HFY05-H and dipyridamole were similar, and the effects of both were significantly better (P < 0.05) than those of LP-HFY05-L." (PMID 35308280, 2022). "Our study would confirm an overexpression of IL-6 specifically within the cardiac tissue, supporting the hypothesis that SARS-CoV-2 directly affects the heart, potentially leading to endothelial injury, inflammatory cytokine storm syndrome, hypercoagulability, or thrombosis." (PMID 41472298, 2025). "Additionally, IL-6 may induce an increase in the expression of fibrinogen and factor VIII, as well as thrombogenesis and platelet hyperactivity, which may promote both arterial and venous thrombosis." (PMID 34069173, 2021). "Neutrophil extracellular traps (NETs), cytokine surges (e.g., IL-6, TNF-α), and brain-derived extracellular vesicles carrying procoagulant microparticles may converge on the pulmonary vasculature, creating a fertile ground for in situ thrombosis even in the absence of deep vein thrombosis (DVT)." (PMID 41149789, 2025).
chronic heart failure (95 papers, 2008 to 2026). "The IL-6 levels were independently associated to mortality in elderly patients with chronic heart failure." (PMID 33535417, 2021). "Elevated levels of circulating TNF-α and IL-6 are associated with the development of congestive heart failure and mortality in congestive heart failure patients." (PMID 26266925, 2014). "According to our results, IL-6 could be an independent factor associated with mortality in elderly patients with chronic heart failure despite model adjustment by age and left ventricular ejection fraction, which are well-known factors associated with poor prognosis and mortality in this entity." (PMID 33535417, 2021). "An analysis of the The BIOlogy Study to TAilored Treatment in Chronic Heart Failure (BIOSTAT-CHF) cohort in 2329 patients with an LVEF ≤ 40% demonstrated an independent relationship between elevated IL-6 levels and hard CV outcomes." (PMID 41196450, 2025). "Congestive heart failure is associated with an elevated production of inflammatory cytokines, specifically TNF-α and IL-6." (PMID 40364122, 2025). "Specifically, monoclonal antibodies to ADRB1 stimulated in vitro proliferation of T cells obtained from the blood of patients with chronic heart failure, and also increased the production of interleukin-6 by these cells." (PMID 40869214, 2025). "In patients with chronic heart failure, increased serum levels of inflammatory cytokines, such as IL-6 and TNF-α as well as the soluble adhesion molecules sICAM-1 and sVCAM-1 have repeatedly been detected, suggesting a vascular pro-inflammatory state." (PMID 36979897, 2023). "Accordingly, 6 weeks of cycle ergometry reduced sTNFR-II concentrations and maintained TNF-α and IL-6 in elderly patient with chronic heart failure." (PMID 33936044, 2021). "The concentration of proinflammatory cytokines, i.e., TNFα and IL-6 measured in supernatants of human peripheral blood mononuclear cells of a patient with chronic heart failure were inhibited in a dose-dependent manner by furosemide treatment." (PMID 34768805, 2021). "Increased levels of TNF-α and IL-6 are related with the development of congestive heart failure and mortality in patients with congestive heart failure." (PMID 33752661, 2021). "Another measured parameter, whose elevated circulating levels are connected with congestive heart failure, was IL-6." (PMID 32392882, 2020). "A non-randomized controlled trial reported that music therapy significantly lowered plasma interleukin-6 and catecholamine levels, in addition to significantly lowering the complications of congestive heart failure." (PMID 32992767, 2020). "Trait positive affect has also been linked to lower stimulated IL-6 levels in a healthy, community sample, and lower IL-6 in chronic heart failure patients." (PMID 29924291, 2019). "Elevated CTRP1 levels in circulation increased IL-6 mRNA levels in congestive heart failure and induced aldosterone release through JAK2-STAT3 signaling pathways." (PMID 31083558, 2019). "TNF-α, IL-1β and IL-6 were the main pro-inflammatory cytokines identified as contributors to the syndrome of chronic heart failure." (PMID 29881417, 2018). "Chronic heart failure is also associated with increased levels of circulating pro-inflammatory cytokines, i.e., tumor necrosis factor-α (TNF-α), interleukin-1 (IL-1), and interleukin-6 (IL-6)." (PMID 29562608, 2018). "Similar results were observed in a meta-analysis that evaluated of the effects of fish oil supplementation in patients with chronic heart failure, showing that circulating TNFα, IL-1β, and IL-6 decreased after 3 to 12 months of follow-up." (PMID 28599665, 2017). "In contrast, previous studies reported that the HDAC inhibitor mocetinostat decreased IL-6 expression in congestive heart failure myocardium and cardiac fibroblasts." (PMID 28194150, 2016). "Glycoprotein-130 (gp130) is the common receptor of IL-6, which is elevated in patients with chronic heart failure." (PMID 23740214, 2013).
chronic heart failure (continued). "In small-sized studies including patients with chronic heart failure, SUAwas associated positively with TNF- α and IL-6." (PMID 21625475, 2011). "In congestive heart failure, circulating IL-6 inversely correlates with AHA functional classification, ejection fraction, and survival." (PMID 19936194, 2008). "Tumor necrosis factor-α (TNF-α), IL-6, and IL-1 have all been observed to be elevated in both humans and animal models of chronic heart failure." (PMID 19936283, 2008). "Additionally, when analysing only patients with chronic heart failure (excluding acute heart failure patients), the Improvement In cardiac function (EF, 6MWT) and Inflammatory markers (IL-6, TNF-α) remained significant, further supporting the findings." (PMID 40951892, 2025). "For example, a study involving two weeks of hot spring bathing revealed a reduction in circulating IL-6 concentration among patients diagnosed with chronic heart failure, highlighting the potential therapeutic impact of heat stress on modulating inflammatory responses." (PMID 37870668, 2024). "In patients with chronic heart failure, elevated circulating levels of IL-6 have been reported." (PMID 29875701, 2018). "The causes of increasing IL-6 levels in ESRD patients is multifaceted including decreased renal elimination of IL-6, increased production of IL-6 from oxidative stress, or from comorbidities such as congestive heart failure." (PMID 28474577, 2017). "Both HIV-associated cardiomyopathy and chronic heart failure have been associated with activation of the immune system leading to the pathogenic overproduction of several proinflammatory cytokines, including TNF-α, IL-1β, IL-6 and IL-18." (PMID 21203448, 2010). "In addition, an inverse relationship between CYP2C19 activity and plasma TNF-α or IL-6 concentrations has been reported in patients with congestive heart failure." (PMID 18854824, 2008). "Interestingly, n-3 PUFAs supplementation in the form of capsules (2g n-3 PUFAs per day/3 months) significantly decreased IL-6 and TNFα levels in patients with chronic heart failure, and CRP and IL-6 levels were significantly decreased in overweight women with an inflammatory phenotype." (PMID 34440006, 2021). "The plasma metabolite ethyl salicylate was correlated positively with pro-inflammatory factors, including IL-6 and TNF-α, in elderly patients with chronic heart failure." (PMID 40121482, 2025). "In a murine model of congestive heart failure (CHF), HDAC1 and HDAC2 also contributed to MF by participating in the IL‐6/STAT3 signalling pathway." (PMID 40497340, 2025). "Patients in chronic heart failure also exhibit higher levels of pro-inflammatory cytokines including TNF-α, IL-6, IL-1β, and C-reactive protein." (PMID 32125488, 2020). "Linggui Zhugan Decoction significantly inhibited the elevation in the levels of serum IL6, IL18, and IL-10 of the chronic heart failure rats." (PMID 32508942, 2020). "Cytokines produced by monocytes including TNF-α and IL-6 and soluble CD14 are correlated with severe congestive heart failure; also soluble TNF receptor can be a predictor of mortality in the same condition." (PMID 31379862, 2019). "In clinical settings, QSYQ can improve cardiac function through anti-inflammatory effects by reducing TNF-α and IL-6 levels both in AMI and chronic heart failure patients." (PMID 24817581, 2014). "An inverse relationship between plasma cytokine (TNF-α and IL-6) concentrations and CYP2C19 activity has been demonstrated in patients with congestive heart failure." (PMID 18854824, 2008). "In patients with chronic heart failure, both TNF-α and Il-6 have been noted to increase in parallel with plasma catecholamines." (PMID 19936283, 2008). "The prognostic relevance of IL-6 has since been consistently replicated in both acute and chronic heart failure settings, irrespective of left ventricular ejection fraction phenotype." (PMID 41375916, 2025).